UCP2 (uncoupling protein 2)
Diseases named in the same sentence as UCP2 in open-access papers (continued):
Sharing a sentence is not in itself a finding about the gene and the disease.
glioma (8 papers, 2017 to 2025). A benign or malignant brain and spinal cord tumor that arises from glial cells (astrocytes, oligodendrocytes, ependymal cells). "In gliomas, UCP2 overexpression has been linked to poor prognosis, suggesting its potential role in tumor progression." (PMID 41403699, 2025). "Without single-cell RNA sequencing (scRNA-seq) data, it is challenging to accurately identify the specific cellular subpopulations, such as glioma stem cells, malignant astrocytes, or tumor-associated macrophages, where UCP2 is highly expressed." (PMID 41403699, 2025). "More notably, in an analysis of Kaplan-Meyer curves based on gene expression the TCGA GBMLGG shows that, across low- and high-grade gliomas, higher UCP2 expression is associated with significantly shorter median survival when compared to low UCP2 expression (High=26.4, Low=87.5 months)." (PMID 33763373, 2021). "Furthermore, UCP2 expression was associated with radiation resistance in glioma." (PMID 41403699, 2025). "Consistent with TCGA results, elevated UCP2 expression correlated significantly with poorer prognosis in glioma patients (CNS WHO grades 2–4)." (PMID 41403699, 2025). "This study integrates bioinformatics and experimental validation to perform a comprehensive pan-cancer analysis of the UCP family, emphasizing UCP2’s role in glioma malignancy and treatment response." (PMID 41403699, 2025). "Genetic and epigenetic analyses in this study demonstrate that DNA methylation acts as a key regulatory mechanism for UCP2 expression in various cancers, including glioma." (PMID 41403699, 2025). "Our integrated analysis and in vitro functional data highlight UCP2 as a potential multifaceted oncogenic factor with prognostic and therapeutic relevance in glioma." (PMID 41403699, 2025). "This integrative research identifies UCP2 as a potential key regulator of glioma progression, EMT, and radiation resistance in preclinical models." (PMID 41403699, 2025). "In vitro functional confirmed that UCP2 knockdown inhibits glioma cell migration, invasion, and EMT, and enhances cells sensitivity to X-ray irradiation." (PMID 41403699, 2025). "Cellular experiments further revealed that UCP2 mediates radiotherapeutic sensitivity in glioma cells, and inhibition of UCP2 expression enhances radiation-induced cell death." (PMID 41403699, 2025). "Induction of UCP2 with increased ROS levels has previously been shown in rat c6 glioma cells upon exposure to diesel exhaust particles." (PMID 39047637, 2024). "As ROS increases and gliomas advance in grade, so too does UCP2 expression rise and the tumor become more dependent on glycolytic metabolism." (PMID 33763373, 2021). "Our results indicated that UCP2 is physiologically important in modulating the generation of ROS from mitochondria of C6 glioma cells exposed to DEPs." (PMID 34439417, 2021). "Rising levels of cytotoxic ROS have been shown to directly correlate both with increased glioma grade and with UCP2 expression." (PMID 33763373, 2021). "Combining UCP2-targeted agents with conventional radiotherapy or immunotherapy could yield synergistic therapeutic effects, especially in UCP2-high glioma subtypes." (PMID 41403699, 2025). "Patients with high UCP2 expression exhibited worse survival outcomes following radiotherapy, suggesting that UCP2 may be involved in the radiation resistance of glioma cells." (PMID 41403699, 2025). "These in vitro results suggest that UCP2 could serve as a potentially therapeutic target and a prognostic biomarker in glioma patients, warranting further investigation." (PMID 41403699, 2025). "Our bioinformatic investigation identified UCP2 as a prominent prognostic marker within the UCP family, with high expression associated with unfavorable outcomes in various tumors, response to immunotherapy, and reduced efficacy of radiotherapy in glioma." (PMID 41403699, 2025).
glioma (continued). "Mechanistically, UCP2 may promote glioma cell survival by enhancing glycolysis (the Warburg effect), mitigating oxidative stress, and conferring resistance to chemotherapy-induced apoptosis." (PMID 41403699, 2025). "This study establishes UCP2 as a prognostic indicator and potential therapeutic target for glioma." (PMID 41403699, 2025). "Next studies should explore whether combining UCP2 inhibition with radiotherapy improves therapeutic efficacy in preclinical glioma models." (PMID 41403699, 2025). "UCP2 expression was shown to positively correlate with tumor grade in both the CGGA RNA-seq database containing 625 low-grade glioma samples and 388 high-grade glioma samples and the TCGA GBMLGG database containing 515 low grade and 152 high-grade glioma samples (p<0.05)." (PMID 33763373, 2021). "Here we sought to investigate the potential role UCP2 could serve as a biomarker to stratify glioma patients for adjunctive metabolic therapies as well as review the implications of prolonged ROS elevation leading to UCP2 overexpression in malignancy." (PMID 33763373, 2021). "Additionally, high UCP2 expression is known to favor a highly glycolytic metabolic profile, therefore suggesting that more aggressive gliomas may have an increased dependency on glycolysis and may be more susceptible to anti-glycolytic treatments." (PMID 33763373, 2021). "Similarly, following UCP2 levels may aide in the surveillance of low-grade gliomas progressing into more aggressive phenotypes." (PMID 33763373, 2021). "UCP2 expression could potentially serve as a biomarker to stratify patients for adjunctive anti-tumor metabolic therapies, particularly in adult and pediatric gliomas." (PMID 33763373, 2021). "UCP2 expression could potentially serve as a biomarker to stratify patients for adjunctive anti-tumor metabolic therapies, such as glycolytic inhibition alongside current standard of care, particularly in adult and pediatric gliomas." (PMID 33763373, 2021). "Clinically, upregulation of UCP2 has been observed in NSCLC tissues compared to adjacent normal tissues as well as in glioma (GLC) and gallbladder cancer." (PMID 39859313, 2025). "This potential effect of UCP2 on the microenvironment is consistent with previous studies showing that gliomas and GBMs are “immuno-cold”, and are oftentimes not engaged or targeted by patients’ immune systems in immunotherapy clinical trials." (PMID 33763373, 2021). "Several cancers, including gliomas, have been observed to upregulate UCP2 expression when compared with their non-neoplastic cells of origin." (PMID 33763373, 2021).
neuroblastoma (8 papers, 2012 to 2025). Neuroblastoma (NB) is the most common solid, extracranial childhood tumor. "Glutamine was found to increase UCP-2 expression in the inner membrane of neuroblastoma cells, as a mechanism of defense against ROS." (PMID 36675195, 2023). "The presence of UCP2 in the mouse embryonic stem cell clone D3 and neuroblastoma cells evaluated in the present study is in agreement with our formerly proposed distribution pattern of UCP2." (PMID 24523901, 2014). "Although this result was to be expected, to our knowledge, UCP2's presence in neuroblastoma cells was experimentally demonstrated for the first time." (PMID 24523901, 2014). "Notably, the neuroblastoma cell line, usually used as a model for primary neurons, expresses UCP2 instead of UCP4 coinciding with the expression of cancer cell markers and glycolytic cell metabolism." (PMID 29988383, 2018). "Overexpressing UCP4 in SH-SY5Y neuroblastoma cells resulted in lower oxidative stress, but also unexpectedly higher cellular ATP levels, which was in discrepancy with the effects of its homologues, UCP2 and UCP5." (PMID 22427795, 2012). "Moreover, inhibiting AMPK abrogates the reduction in oxidative stress caused by irisin in neuroblastoma cells treated with PrP106–126, indicating that the uncoupling-induced AMPK activation is essential for mitigating oxidative stress in PrP106–126-treated cells with impaired UCP2 function." (PMID 39900919, 2025). "We found that UCP2 expression was significantly induced by mitochondrial toxin MPP+, and overexpressing UCP4 completely abolished the induction of UCP2 in these neuroblastoma cells." (PMID 22427795, 2012). "The detection of UCP2 in cell lines (neuroblastoma, BV-2) shown in this work may indicate that metabolism of neuroblastoma cells is not comparable to that of native neurons." (PMID 24523901, 2014).
non-small cell lung carcinoma (8 papers, 2017 to 2025). A group of at least three distinct histological types of lung cancer, including non-small cell squamous cell carcinoma, adenocarcinoma, and large cell carcinoma. "Furthermore, circUCP2 regulates the malignant behavior of non-small cell lung cancer through the miR-149/UCP2 pathway." (PMID 39866227, 2025). "Since mitochondrial Ca2+ uptake is essential for mitochondrial metabolic activity, we manipulated the expression of PRMT1 and UCP2, proteins known to affect the mitochondrial Ca2+ uptake machinery, to investigate their effect on human non-small-cell lung cancer cell lines A549, Calu-3 and H1299." (PMID 29113301, 2017). "For instance, in non-small cell lung cancer (NSCLC), hypoxia-inducible factor alpha (HIF1α) downregulated PPARG expression, which, subsequently, decreased the expression of uncoupling protein 2 (UCP2)." (PMID 41148824, 2025).
Parkinson disease (8 papers, 2006 to 2022). A progressive degenerative disorder of the central nervous system characterized by loss of dopamine producing neurons in the substantia nigra and the presence of Lewy bodies in the substantia nigra and locus coeruleus. "Increased levels of ROS, the principle known inducer of uncoupling protein 2 (UCP2), which typically mediates inducible proton leak, have been measured in pink-1 deficient cell lines and in mitochondria isolated from Parkinson’s disease patients." (PMID 26106885, 2015). "Though less direct than the mouse studies, the work with primates suggests that UCP2 activators are strong therapeutic candidates to treat Parkinson’s disease and possibly other neurological conditions." (PMID 35628482, 2022). "The studies on the mouse model of Parkinson’s disease confirmed our earlier findings in a primate model where we activated UCP2 by feeding the animals a UCP2 activator, Coenzyme Q10 (CoQ10)." (PMID 35628482, 2022). "For example, UCP2 overexpression in mice protects neurons in the substantia nigra of a Parkinson’s disease model." (PMID 28771482, 2017). "UCPs promote neuroprotective effects by diminishing oxidative stress in models of Parkinson disease, focal cerebral ischemia seizures, and brain trauma, and UCP2 itself exerts protective effects in EAE." (PMID 28680531, 2017). "Since ROS production and oxidative damage are involved in most neurodegenerative disorders, UCP2 induction was proposed to have a potential therapeutic effect in the treatment of epilepsy, Parkinson's disease, Alzheimer's disease, brain hypoxia and stroke." (PMID 16968550, 2006). "A number of studies suggest that UCP2 functions in neuroprotection, including following cerebral ischemia or traumatic injury and prevention of seizures or Parkinson's disease." (PMID 16968550, 2006). "In a mouse model of Parkinson’s disease, we found that transgenic mice overexpressing UCP2 retained significantly more nigral dopamine neurons and had higher striatal dopamine levels after MPTP treatment than wild type (36% cell loss vs. 62% loss in substantia nigra)." (PMID 35628482, 2022). "Additionally, studies have shown how the most common genetic cause of Parkinson's disease, G2019S mutations in the leucine-rich repeat kinase 2 gene (LRRK2), displayed uncoupling and low RCR implicating UCP2 and -4 proteins." (PMID 28360103, 2017). "Indeed, mice with enhanced Ucp2-expression in the hippocampus, substantia nigra, or striatum, resisted to neurodegeneration in models of epilepsy, Parkinson's disease, and global ischemia." (PMID 22905184, 2012). "UCP2, in fact, was shown to have a neuroprotective effect in a mouse model of Parkinson's disease." (PMID 16968550, 2006). "This interpretation is backed up by the fact that UCP2 polymorphisms have not been reported in genome-wide association studies (GWAS) that investigated genetic factors underlying risk of Alzheimer’s disease or Parkinson’s disease." (PMID 28771482, 2017). "While most of the current data for the involvement of uncoupling proteins in neurodegenerative disease come from studies on UCP2, there is some evidence that UCP4 and UCP5 may play a role in Parkinson’s disease as well." (PMID 35628482, 2022).
cardiomyopathy (7 papers, 2013 to 2024). A disease of the heart muscle or myocardium proper. "Another study in LPS-induced cardiomyopathy showed that when UCP2 was upregulated, cytochrome c and caspase-3 were decreased, whereas Beclin-1 and LC3 were enhanced, indicating the position of UCP2 in crosstalk between apoptosis and autophagy." (PMID 35706715, 2022). "Recently, a link has emerged between UCP2 cytoplasmic accumulation and mitophagy stimulation, particularly with respect to cardiomyopathies, including IR injury." (PMID 35052662, 2022). "There is no relevant research involving the function of melatonin in LPS-induced cardiomyopathy, it is unclear whether the specificity expression of UCP2 in the different organs and the different models." (PMID 29547569, 2018). "Changes in UCP2 expression could be observed before the overt development of cardiomyopathy, which can be explained by physiological stimulation of UCP2 following adrenergic activation." (PMID 30116205, 2018). "Likewise, UCP2 expression was reduced in the doxorubicin- and streptozotocin-induced cardiomyopathy models." (PMID 30116205, 2018). "This study is the first one to show the possible mechanism that melatonin may influence UCP2 expression in LPS-induced cardiomyopathy." (PMID 29547569, 2018). "Both in vitro and in vivo evaluations revealed that UCP2 had protective effects against LPS-induced cardiomyopathy via regulating the balance between apoptosis and autophagy in cardiomyocytes, and it may play a role in myocardial function homeostasis and cardiomyocytes activity." (PMID 35706715, 2022). "Furthermore, melatonin could elevate mitochondrial uncoupling protein 2 (UCP2) to decrease the production of mROS and inhibit autophagy in LPS-induced cardiomyopathy." (PMID 38273825, 2023).
epilepsy (7 papers, 2012 to 2021). A brain disorder characterized by episodes of abnormally increased neuronal discharge resulting in transient episodes of sensory or motor neurological dysfunction, or psychic dysfunction. "In the present study, we demonstrated that rats subjected to the animal model of epilepsy induced by pilocarpine had increased expression of UCP2 in the hippocampus during the early silent phase (between 3–5 days after SE)." (PMID 30159115, 2018). "Although further studies are needed to identify the molecular pathways of epileptogenesis, our results contribute to the increasing knowledge about the activity of the UCP2-survival-apoptosis axis in epilepsy." (PMID 30159115, 2018). "This higher decrease in bcl2 : bad mRNA ratio suggests a more pronounced apoptotic cell death related with UCP2 silencing in the silent phase of the pilocarpine-induced epilepsy model." (PMID 30159115, 2018). "In the present study, we tested the hypothesis that UCP2 can act as an endogenous protective factor against epilepsy-induced damage, using antisense oligonucleotide (ASO) administration, in an experimental pilocarpine model." (PMID 30159115, 2018). "We hypothesized that UCP2 as a neuroprotector may counterbalance the neuronal damage provoked by SE induced by pilocarpine in the experimental epilepsy model." (PMID 30159115, 2018). "Therefore, we analyzed the time course expression of UCP2 mRNA during the all phases of this experimental epilepsy model." (PMID 30159115, 2018). "The relation between UCP2 and AKT has already been described, although its relevance to epilepsy remains unclear." (PMID 30159115, 2018).
cervical cancer (6 papers, 2015 to 2025). A primary or metastatic malignant neoplasm involving the cervix. "UCP2 expression in human cervical cancer cells and human ovarian serous carcinoma cells was inhibited by genipin, which it significantly augmented cisplatin sensitivity when UCP2 was repressed in vitro." (PMID 35628447, 2022). "The protein expression results confirmed that UCP2 silencing contributed to overcoming the radioresistance of cervical cancer cells by apoptosis, G2/M arrest, and DNA damage." (PMID 32190174, 2020). "The mechanism of enhanced radiosensitivity induced by mitochondrial uncoupling protein UCP2 was investigated in HeLa cells to provide a theoretical basis as a novel target for cervical cancer treatment." (PMID 32190174, 2020). "The effect of UCP2 knockdown on the repair of DNA damage in cervical cancer cells was investigated by assaying γH2AX protein level at different times after irradiation." (PMID 32190174, 2020). "The overall results support the potential utility of UCP2 as an antitumor target in cervical cancers and as a radiosensitizer for HeLa cells." (PMID 32190174, 2020). "This study found a significant elevation of UCP2 expression and ROS production in irradiated HeLa cervical cancer cells that inhibited cell proliferation and promoted apoptosis." (PMID 32190174, 2020). "In cervical cancer patients, however, UCP2 serves as a marker of positive prognosis." (PMID 41367865, 2025). "These proteins may serve as valuable prognostic markers for patients with precursor cervical lesions, and UCP2 expression, in particular, could be beneficial for predicting outcomes in cervical cancer patients." (PMID 41367865, 2025). "UCP2 knockdown has been shown to arrest the proliferation of cervical cancer-derived cells." (PMID 41367865, 2025). "An increase in the radiosensitivity of cervical cancer cells caused by UCP2 has not been previously reported." (PMID 32190174, 2020). "The study results suggest that the genes coding UCP2 may be radiation induced, with similar background expression in different types of cervical cancer cells." (PMID 32190174, 2020). "Few data are available on the role of UCP2 in cervical cancer." (PMID 32190174, 2020). "UCP2 inhibition augmented the radiosensitivity of cervical cancer cells, and it may be a potential target of radiotherapy of advanced cervical cancer." (PMID 32190174, 2020). "UCP2 may be a target molecule for the development of novel cervical cancer-specific radiosensitizers." (PMID 32190174, 2020). "UCP2 induction by Salmonella was also confirmed in human macrophage-like THP-1 cells and human cervical cancer cells (HeLa)." (PMID 26659006, 2015). "Our findings suggest UCP2 should be considered in cervical cancer, not just as a prognostic marker but also as an indicator of treatment response, especially for patients undergoing immunotherapy." (PMID 41367865, 2025). "There is limited data on UCP2’s potential role in cervical cancer and virtually none regarding precursor lesions." (PMID 41367865, 2025).